LGALS3BP (galectin 3 binding protein)
Description:
Promotes integrin-mediated cell adhesion. May stimulate host defense against viruses and tumor cells.
Synonyms: M2BP; MAC-2-BP; 90K; BTBD17B; TANGO10B; gp90; CyCAP
Tractability: Antibody: UniProt places it where antibodies can reach, with high confidence; its Gene Ontology location is reachable by antibodies, with high confidence; UniProt predicts a signal peptide or a membrane-spanning region. PROTAC: ubiquitination databases record sites on it; its protein half-life has been measured.
Gene: Protein-coding gene on chromosome 17 (78,971,238 to 78,979,962, reverse strand). Ensembl gene ENSG00000108679.
Subcellular location: Secreted; Secreted, extracellular space, extracellular matrix
Pathways (Reactome):
Hemostasis: Platelet degranulation
Gene Ontology:
Molecular function: protein binding; scavenger receptor activity
Biological process: cellular defense response; signal transduction; vesicle-mediated transport
Cellular component: blood microparticle; extracellular exosome; extracellular matrix; extracellular region; platelet dense granule lumen; membrane
Genetic constraint (gnomAD): Loss-of-function variants: 28 observed, 24.09 expected, observed/expected ratio (o/e) 1.16, 90% interval 0.86 to 1.59. The upper end of that interval is the gene's LOEUF score, 1.59, which puts it in group 6 of 6, group 1 being the genes least tolerant of losing a copy. Missense variants: 717 observed, 769.37 expected, observed/expected ratio (o/e) 0.93, 90% interval 0.88 to 0.99. Synonymous variants: 334 observed, 336.04 expected, observed/expected ratio (o/e) 0.99, 90% interval 0.91 to 1.09.
Homologues: Orthologues: chimpanzee LGALS3BP (99% identical), macaque LGALS3BP (93% identical), rabbit LGALS3BP (72% identical), mouse Lgals3bp (68% identical), pig LGALS3BP (67% identical), guinea pig LGALS3BP (66% identical), rat Lgals3bp (65% identical), zebrafish si:dkey-14d8.20 (14% identical), Drosophila melanogaster Loxl2 (4% identical). Paralogues in human: SSC4D (21% identical), DMBT1 (19% identical), CD163 (15% identical), CD163L1 (15% identical), SSC5D (15% identical), PRSS12 (13% identical), SCART1 (13% identical), CD6 (13% identical), CD5L (11% identical), LOXL2 (10% identical), LOXL4 (9% identical), LOXL3 (9% identical), and 3 more.
Diseases named in the same sentence as LGALS3BP in open-access papers:
LGALS3BP is named in the same sentence as 154 diseases in open-access papers, as found by Europe PMC text mining. Sharing a sentence is not in itself a finding about the gene and the disease. The quoted sentences say what the papers report.
liver fibrosis (60 papers, 2015 to 2025). "Experimental evidence from hepatocyte-specific Lgals3bp-knockin mice revealed exacerbated hepatic fibrosis accompanied by elevated Tgfb1 levels." (PMID 41209003, 2025). "In this study, we focused on the liver fibrosis marker, M2BPGi, a glycosylated galectin-3-binding protein derived from the stromal cells of cirrhotic liver." (PMID 32624579, 2020). "Moreover, LGALS3BP also contributes to hepatic fibrosis and carcinogenesis via regulation of TGF‐β1 signaling." (PMID 41308656, 2025). "Previous studies have demonstrated that Lgals3bp activates the TGF-β1 signaling pathway, thereby promoting hepatic fibrosis in mice." (PMID 41209003, 2025).
hepatocellular carcinoma (27 papers, 2014 to 2026). A malignant tumor that arises from hepatocytes. "It is reported that elevated expression of LGALS3BP in either serum or tumor tissue is associated with poor clinical outcomes in patients with breast cancer, lung cancer, pancreatic carcinoma, hepatocellular carcinoma, pleural mesothelioma, and neuroblastoma." (PMID 35038949, 2022). "At molecular level, data were provided showing that, along with melanoma, also in the hepatocellular carcinoma Hu-H7 adhesion on LGALS3BP is mediated by integrins α1β1 and αvβ1." (PMID 34565385, 2021). "Furthermore, miR-4660 delivery via exosomes inhibits OPN-promoted hepatoma cell aggression by targeting LGALS3BP, highlighting a potential therapeutic target against cancer metastasis." (PMID 42005698, 2026). "A research group investigated prognostic significance of LGALS3BP in hepatocellular carcinoma (HCC) in several studies." (PMID 34565385, 2021). "LGALS3BP is suspected to be a tumor suppressor due to its under-expression in prostate cancer, while CSNK2A2 over-expression promotes tumor progression, particularly in hepatocellular carcinoma." (PMID 39941055, 2025). "Galectin-3-binding protein (LG3BP), a protein promoting tumor growth, was found in the serum-derived exosomes of hepatocellular carcinoma (HCC; liver cancer) patients with remarkably increased expression compared to that of the healthy control group." (PMID 35757760, 2022).
viral infection (21 papers, 2017 to 2025). "Recent studies report that LGALS3BP is upregulated during viral infections, such as HIV and herpesvirus, where it acts as a modulator of antiviral immunity." (PMID 41090922, 2025). "In the case of viral infection, Lgals3bp forms complex with Traf6 or Traf3, and subsequently recruits TAK1 and TBK1, which then signal the translocation of the transcription factors NF-κB, IRF3, and IRF7 from the cytoplasm to the nucleus." (PMID 38279161, 2024). "Lgals3bp expression is induced by viral infection and upon exposure to pro-inflammatory, such as IFN-α, IFN-β, IFN-γ, and TNF-α." (PMID 37491623, 2023). "Expression of LGALS3BP is stimulated by IFNs, resulting in upregulated 90K serum concentrations in individuals with viral infections, including HIV-1, HCV, hantaviruses, and dengue virus." (PMID 37162650, 2023). "Along with these proteins, several other viral infection induced proteins such as LGALS3BP, GOLM1, and LTA4H were also increased." (PMID 35958562, 2022). "On the other hand, LGALS3BP expression was found to be induced by viral infection and in response to a variety of cytokines unleashed by inflammatory processes, including IFN-α (Interferon), IFN-β, IFN-γ, TNF-α (Tumor Necrosis Factor)." (PMID 34565385, 2021). "On the sixth day, the amounts of galectin-3-binding protein (Lgals3bp), Hpx and S100a8 in the infected mouse blood consistently increased during viral infection, whereas their expression levels in blood were all decreased by HYQ administration (p < 0.05)." (PMID 34867309, 2021). "The protein known as lectin galactoside-binding soluble 3-binding protein (LGALS3BP), Mac-2-binding protein (Mac-2BP), or 90K is a secretory glycoprotein, and its serum levels are observed to be elevated in several cancers and viral infections." (PMID 29207493, 2017). "Our findings align with previous studies showing that LGALS3BP is upregulated during viral infections such as HIV, herpesvirus, influenza A virus, vesicular stomatitis virus, and severe acute respiratory syndrome coronavirus 2 (SARS-CoV-2), where it modulates antiviral immunity." (PMID 41090922, 2025). "Galectin-3 binding protein (Gal-3BP) is a multifunctional glycoprotein involved in cell–cell and cell–matrix interactions known to be upregulated in cancer and various viral infections, including HIV-1, HCV, and SARS-CoV-2, with a key role in regulating the antiviral immune response." (PMID 35806317, 2022). "LGALS3BP exhibited antiviral activity toward a broad range of viral infections." (PMID 31404116, 2019). "This combination of immune regulation and viral protein degradation makes LGALS3BP an effective host factor against PRRSV and potentially other viral infections." (PMID 41090922, 2025). "Given its broad-spectrum antiviral activity, LGALS3BP holds promise as a candidate for host-directed therapies, not only for PRRSV but potentially for other viral infections as well." (PMID 41090922, 2025). "The lectin galactoside-binding soluble 3 binding protein (LGALS3BP) is a multifunctional glycoprotein involved in immune responses, defense against viral infections, and cancer progression." (PMID 37041137, 2023). "CRP, LGALS3BP, and HASPA8 have been shown to promote the innate immune response and inflammatory response and maintain cellular environmental homeostasis in viral infection." (PMID 35464963, 2022). "Galectin 3 binding protein (LGALS3BP), also referred to as 90K, is a multifunctional protein that plays significant roles in viral infections, but its role in PRRSV infection is not clearly defined." (PMID 40542445, 2025).
breast carcinoma (19 papers, 1994 to 2025). "Numerous studies have indicated that markedly increased levels of LGALS3BP in serum or tumor tissues have been linked to adverse clinical outcomes in various malignancies, such as neuroblastoma, glioblastoma, breast cancer, and endometrial cancer." (PMID 38944027, 2025). "Monoclonal antibodies in human breast cancer cells can recognize LGALS3BP (a 90 kDa tumor-associated antigen) and in human lung cancer cells." (PMID 38393692, 2024). "LGALS3BP was first discovered from two independent research groups as a 90KDa tumor-associated antigen recognized by SP2 monoclonal antibody in CG-5 human breast cancer cells and by L3 monoclonal antibody in Calu-1 human lung cancer cells." (PMID 34565385, 2021). "In line with this, increased levels of tumor cell associated LGALS3BP were observed at the leading edge of breast cancer biopsies." (PMID 34565385, 2021). "High serum or tissue level of LGALS3BP has been confirmed to be associated with various malignant tumor, like breast cancer and metastasis." (PMID 27825122, 2016). "LGALS3BP (also known as MAC-2BP and 90K protein) was originally identified as a tumor-associated antigen in the culture supernatant of human breast cancer cells." (PMID 23181716, 2012). "Expression of the 90K immunostimulatory antigen LGALS3BP has been inversely correlated with the tumorigenicity of mammary carcinoma, GBM, and other tumor-derived cell lines in athymic mice." (PMID 35865015, 2022). "LGALS3BP was initially identified as a heavily glycosylated protein in tumor tissue and serum from breast cancer patients and lung cancer cell lines." (PMID 35038949, 2022). "High levels of LGALS3BP in serum or tumor tissue of cancer patients were previously reported to be correlated with a poor survival or a more advanced disease in breast cancer." (PMID 35911770, 2022). "Galectin-3-binding protein was found to be increased in the control group, with a mean of 75263.2 pg/ml, compared to breast cancer group which had a mean of 23747.3 pg/ml and a p-value of <0.0001." (PMID 35471994, 2022). "A first report showed that adhesion of ZR-75-1 breast cancer cells to endothelial cells was mediated by endothelial E-selectin and LGALS3BP, thus identifying this latter protein as a novel E-selectin ligand." (PMID 34565385, 2021). "They found that LGALS3BP secreted by the human metastatic breast cancer cells MDA-MB-231 inhibited monocyte-derived fibrocyte differentiation, and, conversely, galectin-3 promoted monocyte-derived fibrocyte differentiation." (PMID 34565385, 2021). "Breast cancer patients sera and breast cancer cell culture media were among the first sources for identification and purification of LGALS3BP." (PMID 34565385, 2021). "Four drug resistance genes (AMIGO2, LGALS3BP, SCUBE2 and WLS) were found to be promising tools for ER+ and HER2- breast cancer risk stratification." (PMID 34760348, 2021). "This suggested a primary role of LGALS3BP in cell adhesion and cancer metastasis, explaining the poor prognosis of breast cancer patients with LGALS3BP overexpressing tumors." (PMID 34565385, 2021). "Immunohistochemical analysis of LGALS3BP expression in several tumors, including breast carcinomas, revealed LGALS3BP positive staining predominantly in cytoplasm." (PMID 23181716, 2012). "The most significant differences in expression pattern were revealed for RAD50 and LGALS3BP in cancer cells of different histological types of breast cancer and for PABPC4 and FAM50A antigens in immune cells infiltrating breast tumors." (PMID 23181716, 2012). "The most significant differences were observed for RAD50 and LGALS3BP antigens in different histological types of breast carcinomas." (PMID 23181716, 2012). "The most significant differences in expression pattern were revealed for RAD50 and LGALS3BP in different histological types of breast cancer and for PABPC4 and FAM50A antigens in immune cells infiltrating breast tumors." (PMID 23181716, 2012).
breast carcinoma (continued). "Current studies have demonstrated that LGALS3BP may be a therapeutic target and biological fabric for breast cancer." (PMID 38393692, 2024). "Three biomarkers, S100A8 (p-value = 0.0069, 7.8-fold increase), S100A9 (p-value = 0.0048, 10.2-fold increase), and Galectin-3 binding protein (p-value = 0.01, 3.0-fold increase) with an increased expression in breast cancer patients were selected for validation using ELISA." (PMID 35471994, 2022). "NF-κB reportedly mediated TNF-α-induced Lgals3bp mRNA expression in breast cancer cells." (PMID 33824294, 2021). "Moreover, administration of rIFN-α-2b to breast cancer patients significantly increased LGALS3BP serum levels over pre-administration values." (PMID 34565385, 2021). "Other studies attempted to understanding the molecular mechanism underlying the negative prognostic role of LGALS3BP in breast cancer." (PMID 34565385, 2021). "Using mass spectrometry we identified two precursor proteins Galectin 3 binding protein (G3BP) and Lysyl oxidase 2-like protein (LOXL2) that associate with eHsp90 in MDA-MB231 breast cancer cell conditioned media and confirmed that LOXL2 binds to eHsp90 in immunoprecipitates." (PMID 24785146, 2014). "Interestingly, breast carcinoma cells overexpressing LGALS3BP, show apoptosis resistance in response to anticancer treatment." (PMID 21858171, 2011). "Finally, the role of LGALS3BP O‐glycosylation was evaluated in terms of breast cancer growth." (PMID 34565385, 2021). "LGALS3BP inhibits the differentiation of monocyte-derived fibrocytes through CD209/SIGN-R1 in mouse spleen and is secreted from breast cancer for metastasis." (PMID 34646273, 2021). "In current study we analyzed six previously identified medullary breast carcinoma autoantigens including LGALS3BP, RAD50, FAM50A, RBPJ, PABPC4, LRRFIP1 with cancer restricted serological profile in different histological types of breast cancer." (PMID 23181716, 2012). "This pilot study made possible to select 4 antigens LGALS3BP, RAD50, PABPC4, and FAM50A as promising candidates for more comprehensive research as potential molecular markers for breast cancer diagnostics and therapy." (PMID 23181716, 2012). "LGALS3BP may be glycosylated by GALNT6 to promote autocrine cell growth; thus, the proliferation of breast cancer cells strongly correlates with the GALNT6-LGALS3BP axis." (PMID 38393692, 2024). "Early works focused on study of LGALS3BP showed its expression in more than 80% of breast cancer tissues, but not in non-cancerous normal mammary gland surrounding the cancer cells." (PMID 23181716, 2012). "This work is a pilot study, which made possible to select 4 potential breast cancer markers (FAM50, PABC4, RAD50, LGALS3BP) for further studies with larger cohorts of patients with different histological types of breast cancer using automated measurement systems for immunohistochemical analysis." (PMID 23181716, 2012). "90K/Mac-2 BP (Mac-2-binding protein), also known as 90K, lectin galactoside-binding soluble 3-binding protein (LGALS3BP) or Galectin-3 binding protein (Gal-3BP), is a N-glycoprotein (PM 70–95 kDa), originally described as a circulating antigen in the supernatant of human breast cancer cells." (PMID 36835367, 2023). "Thus, during this study we described for the first time expression patterns of 6 potential MBC-associated antigens, including LGALS3BP, RAD50, FAM50A, RBPJ, PABPC4, LRRFIP1 in different histological types of breast carcinomas and non-cancerous breast tissues by immunohistochemical analysis." (PMID 23181716, 2012).
colorectal cancer (13 papers, 2015 to 2025). A primary or metastatic malignant neoplasm that affects the colon or rectum. "LGALS3BP exhibits antitumor activity in colorectal cancer via β-catenin ubiquitination, and high LGALS3BP expression is associated with better overall survival in colon cancer patients." (PMID 37041137, 2023). "Indeed, Galectin-3-binding protein (LGALS3BP), gelsolin (Gsn), and Spartin (Spg20), which are associated with a favorable clinical outcome in colorectal carcinoma are downregulated in APLN-expressing cells and upregulated in APLN-DM-expressing cells." (PMID 39962271, 2025). "However, it has been suggested that LGALS3BP is associated with favorable clinical outcomes in colorectal cancer, pleural mesothelioma, and Ewing sarcoma." (PMID 39434140, 2024). "However, it was proposed that LGALS3BP is associated with a favorable clinical outcome in colorectal carcinoma, pleural mesothelioma and Ewing’s sarcoma." (PMID 34565385, 2021). "LGALS3BP protein expression was evaluated by immunohistochemistry in 196 paraffin-embedded, archival primary colorectal cancer tissues." (PMID 26219351, 2015). "A previous report has shown that LGALS3BP (also known as 90K or Mac-2 BP) has antitumor activity in colorectal cancer (CRC) via suppression of Wnt signalling with a novel mechanism of ISGylation-dependent ubiquitination of β-catenin." (PMID 26219351, 2015). "In fact, several studies have also demonstrated the potential anti-tumor activities of LGALs3bp in colorectal cancer, where it suppresses WNT signaling and could promote a good prognosis." (PMID 41279039, 2025). "In 2011, a report discovered the dendritic cell (DC)-specific intercellular adhesion molecule- 3-grabbing non-integrin (DC-SIGN) as a novel interactor of LGALS3BP in colorectal cancer (CRC)." (PMID 34565385, 2021). "Galectin-3-binding protein (LGALS3BP) also known as 90K is involved in tumour growth and progression and was chosen as a model of a tumour marker since it has been found elevated in serum of patients with different types of cancer, such as breast, prostate, and colorectal cancers." (PMID 32875368, 2020).